HK2 (hexokinase 2)
Diseases named in the same sentence as HK2 in open-access papers (continued):
Sharing a sentence is not in itself a finding about the gene and the disease.
melanoma (continued). "This could be explained by the fact that aerobic glycolysis is upregulated in human BRAFV600 melanoma cells via transcriptional regulation of HK2 and GLUT1." (PMID 40956859, 2025). "We evaluated the level of HK2 in a variety of melanoma cell lines." (PMID 40956859, 2025). "Coherently, in silico analysis of a TCGA melanoma dataset (n = 448 patients) revealed that the expression of LDH‐A, HK2 (encoding gene for HKII) and SLC16A3 (encoding gene for the transporter MCT4) inversely correlate with oestrogen‐related receptor alpha (ERRα), a representative female sex marker." (PMID 39888245, 2025). "We found that HK2 depletion decreases cell proliferation of melanoma cells after 6 days." (PMID 40956859, 2025). "Next, we investigated whether HK2 contributes to proliferation properties of melanoma cells via the SOX10 UTR." (PMID 40956859, 2025). "SOX4 regulates melanoma glycolytic metabolism controlling the transcriptional expression of glucose transporter type 1, hexokinase 2, and lactate dehydrogenase A, and activates mTORC1 to promote proliferative signals and cell growth when SOX4 is upregulated by CD147." (PMID 36661515, 2023). "HK2 has been proven to be involved in glycolysis in malignant melanoma cells." (PMID 37539493, 2023). "In addition, immunohistochemistry analysis showed that HK2‐positive cell numbers in melanoma tissues were significantly enhanced." (PMID 37539493, 2023). "To determine whether HK2 could specifically associate with the SOX10 mRNA, we performed HK2 immunoprecipitation (IP) followed by RT-qPCR (RNA ImmunoPrecipitation-RIP analysis) in A375 and A2058 melanoma cells." (PMID 40956859, 2025). "Furthermore, whether circ-FOXM1 regulated the glycolysis of melanoma cells was explored via detecting the levels of glucose consumption, lactate production, and glycolysis key enzymes (including HK2 and PKM2)." (PMID 32183822, 2020). "This is particularly important since HK2 is an attractive target in cancer and since SOX10 is not only critical in melanoma proliferation but also a factor of resistance to immunologic cell death." (PMID 40956859, 2025). "We observed increased levels of HK2 in invasive cell lines (A375, WM35, SKMel10) compared to early invasive melanoma (VGP: WM793), early superficial melanoma with radial growth (RGP: SBCL2) or normal human melanocytes." (PMID 40956859, 2025). "To further validate the direct and specific binding of HK2 to RNA, we performed CLIP assays in melanoma cells following siRNA-mediated HK2 depletion." (PMID 40956859, 2025). "We also compared mRNA expression of glycolytic markers in p3-S melanoma cells respect to S melanoma cells and we confirmed that in anoikis-resistant cells the expression of GLUT1, GLUT3, HK2, PKM2, and LDHA significantly reduced." (PMID 39175551, 2024). "Overexpression of HK2 weakened the inhibitory effects of SPI1 knockdown on the viability, metastasis and glycolysis of melanoma cells." (PMID 37539493, 2023). "In this work, KIF22 interference notably repressed glycolysis in melanoma cells, evidenced by reduced levels of ECAR, lactate production, HK2, PKM2 and LDHA expression as well as elevated levels of OCR." (PMID 37944197, 2023). "Herein, we verified that SPI1 regulated HK2 expression, thereby mediating the AKT1/mTOR signalling pathway and promoting melanoma cell proliferation, metastasis and glycolysis." (PMID 37539493, 2023). "The results showed that, in the absence of PLX, 3BP significantly decreased LDH5 expression in both PLX-resistant melanoma cell lines, whereas it increased MCT1 expression in A375R cells and HK2 expression in SKMEL28R cells." (PMID 36555289, 2022). "Herein, we verified that the circ_0013359 level was conspicuously increased in melanoma and its reduction repressed melanoma cell glycolysis by reducing glucose consumption, lactate production, ECAR, HK2, and LDHA." (PMID 34056112, 2021).
melanoma (continued). "Baicalein and baicalin treatments markedly suppressed gene expression of Glut1, Glut3, HK2, TPI, GPI, and PFK1 in both human and mouse melanoma cells." (PMID 32984331, 2020). "The expression levels of GLUT1, GLUT3, HK2 and LDHA mRNA were downregulated in melanoma cells incubated with the HLA-B,C-specific mAb B1.23.2." (PMID 31454998, 2019). "In melanoma, oncogenic BRAFV600E promotes the mRNA and protein expression of GLUT-1, GLUT-3, and HK2 through the involvement of several transcription factors including HIF-1α, c-Myc, and MONDOA." (PMID 26713093, 2015). "Consistently, HK2 depletion decreased SOX10 protein levels, but not SOX10 mRNA levels, in four different BRAF-mutated (V600E) melanoma cell lines." (PMID 40956859, 2025). "Here, we report that Hexokinase 2 (HK2), a glucose kinase that catalyzes the first step of glycolysis at the outer mitochondrial membrane (OMM), is an RNA-binding protein (RBP) that regulates mRNA translation in melanoma cell lines." (PMID 40956859, 2025). "Conversely, Myc-DDK-SOX10 (ΔUTR) enhances this effect, thereby indicating that the involvement of HK2 on the migration properties of melanoma cells is independent of the SOX10 UTR." (PMID 40956859, 2025). "Furthermore, subsequent experiments indicated that HK2 overexpression weakened the inhibitory effect of SPI1 knockdown on cell viability, metastasis and glycolysis in melanoma cells." (PMID 37539493, 2023). "The regulation of melanoma proliferation, metastasis and glycolysis by HK2 through the AKT/mTOR signalling pathway has not been reported." (PMID 37539493, 2023). "A decrease in the expression levels of various glycolytic genes, including GLUT1, GLUT3, and HK2, lactate and ATP production was observed in a panel of BRAF(V600E) melanoma cell lines treated with the BRAF inhibitor vemurafenib as well as in samples from patients undergoing BRAF inhibitor therapy." (PMID 30487597, 2019). "We hypothesized that metabolic adaptation might be required, and indeed when melanoma cells were cultured in normoxic conditions for 3 weeks, the transcript levels of GLUT1, PDK1 and HK2 were markedly enhanced also in DMBC17 cells." (PMID 31461993, 2019). "Finally, analysis of database of melanoma patients showed a significant correlation between the expression levels of HK2 and MCL1 (p = 2.3e-06, rho = 0.216) –but not BCL-2 (p = 1.98e-01, rho = 0.059) or BCL2L1 (p = 4.57e-01, rho = 0.034)." (PMID 41326406, 2025). "Unlike melanoma samples from patients, where HK2 expression was not altered relative to normal skin, A375 cells exhibited higher HK2 expression compared to skin fibroblasts, which may explain their increased sensitivity to 2DG." (PMID 41155949, 2025). "The HDAC8 promotes the expression of HIF-1α target genes, such as hexokinase 2 (HK2) and glucose transporter protein 1 (GLUT1), by upregulating HIF-1α expression levels and elevating HIF-1α transcriptional activity, which can promote the proliferation and metastasis of melanoma cells." (PMID 39876842, 2024). "However, K103 enzyme, which is the only HK2 functional RT has been demonstrated to be inhibited only by NRTIs and not by NNRTIs in melanoma cell lines in vitro." (PMID 32933538, 2020). "The results implied that the levels of glucose consumption, lactate production, HK2, and PKM2 were all repressed in A2058 and A375 cells by circ-FOXM1 downregulation compared to control groups, indicating that circ-FOXM1 knockdown repressed glycolysis in melanoma cells." (PMID 32183822, 2020). "Importantly, the expression of GLUT-1, GLUT-3, and HK2 is reduced in melanoma specimen from patients treated by pharmacological BRAFV600E inhibitors (BRAFi) and is reexpressed after relapse suggesting a critical role of glycolysis in melanoma progression." (PMID 26713093, 2015).
melanoma (continued). "HK2 plays a vital role in regulating melanoma angiogenesis by promoting aerobic glycolysis and activating the p38‐mitogen‐activated protein kinase (MAPK) pathway, indicating that HK2 might be a candidate gene for melanoma, but specific studies are rarely reported." (PMID 37539493, 2023). "In contrast to HK2, which was not significantly changed, the other 2-DG substrate, GPI, was increased by ~7.6-fold in melanoma." (PMID 41155949, 2025).
bladder cancer (38 papers, 2015 to 2026). "It has been reported that HK2 served as a target gene of miR‐125b, which was negatively associated with miR‐125b expression in bladder cancer cells and laryngeal squamous cell carcinoma cells." (PMID 34664737, 2021). "Analysis of human bladder cancer specimens reveals that HK2 expression positively correlates with MYC and LDHA levels and associates with worse patient survival, particularly in patients with hyperglycemia." (PMID 41951587, 2026). "Our results demonstrated that the CXCL14/CCR7/STAT3 axis significantly promotes the glycolytic shift in bladder cancer cells by upregulating the expression of HK2 and LDHA, two key glycolytic enzymes." (PMID 40898244, 2025). "Single-cell multi-omics further validated HK2 as a biomarker for noninvasive bladder cancer detection, demonstrating 90% sensitivity and 98% specificity in urine-based liquid biopsies." (PMID 40693266, 2025). "For glucose metabolism, 2DG, an HK2 inhibitor, has been shown to reduce bladder cancer cell viability, proliferation, migration, and invasion in vitro and in vivo preclinical UBC models." (PMID 41281744, 2025). "Activates mTOR, inducing signal transducer and activator of transcription 3 protein, and inhibiting miR-143, thereby upregulating hexokinase 2 and glycolysis in bladder cancer." (PMID 38544804, 2024). "LncUCA1 activates mTOR, by inducing signal transducer and activator of transcription 3 protein, and inhibiting miR-143, thereby upregulating hexokinase 2 and glycolysis in bladder cancer." (PMID 38544804, 2024). "Hyperglycemia upregulates HK2 and promotes its nuclear localization in bladder cancer cells, where nuclear HK2 forms a complex with MYC to co-activate HK2 and LDHA transcription, thereby enhancing glycolysis, stemness, and tumor growth in hyperglycemic conditions." (PMID 41951587, 2026). "Similarly, in bladder cancer, LC-MS/MS revealed that HK2-mediated glycolytic flux drives cisplatin resistance, prompting the development of the HK2 inhibitor, which synergized with sorafenib to inhibit tumor growth." (PMID 40693266, 2025). "Moreover, studies have shown that the overexpression of glucose metabolism-related proteins, such as GLUT1 and HK2, correlates with increased aggressiveness and poor prognosis in bladder cancer." (PMID 41281744, 2025). "Moreover, SNHG1 enhances HK2 expression by competitively regulating miR-143-3p expression, thus promoting bladder cancer cell proliferation." (PMID 38706912, 2024). "Hexokinase 2 remained as an independent prognostic factor, which led us to further exploit the functional effects of the hexokinase 2 inhibitor 2-deoxy-D-glucose in “in vitro” and “in vivo” preclinical models of bladder cancer." (PMID 36765947, 2023). "On the other hand, some studies have shown that aerobic glycolysis could be promoted by UCA1 in bladder cancer cells by targeting miR-16 and up-regulating hexokinase-2, thus affecting their malignant potential." (PMID 27517147, 2016). "Targeted regulation of certain processes of glucose metabolism reprogramming in bladder cancer cells (such as targeting HK2) can inhibit the proliferation of bladder cancer cells, and abnormal glucose metabolism may contribute to drug resistance to chemotherapy drugs." (PMID 41281744, 2025). "Moreover, GSDMB modulated the glycolysis by up-regulating the expression of HK2 in bladder cancer cells, suggesting that GSDMB might be involved in regulating the glucose metabolism of bladder cancer cells through STAT3-related signaling pathways." (PMID 34326684, 2021). "In addition, UCA1 promoted glycolysis by upregulating hexokinase 2 in bladder cancer cells." (PMID 27009634, 2016). "In bladder cancer, UMUC-3 cells show high HK2 expression and low HK1 expression; the inhibiting HK2 showed reduced glucose consumption, lactic acid production, and glycolysis." (PMID 35265223, 2022).
bladder cancer (continued). "STAT3 has been shown to affect cellular metabolism, through increased glucose consumption, and lactate production in bladder cancer, through increased transcription of LDHA, ENO2, HK2, and IGFBP3." (PMID 36230984, 2022). "In our study, ex vivo transcript analysis of human bladder cancer tissues demonstrated the upregulation of glycolytic genes GLUT1 and HK2 together with the downregulation of PGC-1α, supporting the presence of a metabolic switch toward glycolysis." (PMID 36233054, 2022). "For example, lncRNA UCA1 could activate the mTOR pathway, mediate the regulation of urothelial cancer associated 1 (UCA1) to HK2 through activation of signal transducer and activator of transcription 3 (STAT3), then promote glycolysis, exert promotion effects on tumorigenesis in bladder cancer." (PMID 36072431, 2022). "Our current results suggest that TAZ is vital for glycolysis in bladder cancer cells and functions by regulating the expression of PFKFB3, HK2 and GLUT1, which serve as key components in glycolysis." (PMID 33499877, 2021). "In bladder cancer, lncRNA UCA1 is overexpressed and promotes glycolysis by upregulation of hexokinase 2 (HK2), and also promotes aerobic glycolysis." (PMID 34560889, 2021). "Overexpressed GSDMB promoted cancer cell growth via interacting with STAT3 to elevate the phosphorylation level of STAT3, which increased the expression of HK2, LDNA, ENO2, and IGFBP3 to enhance the glycolysis of bladder cancer cells." (PMID 34326684, 2021). "It was found that LncUCA1 promotes aerobic glycolysis by upregulating hexokinase 2 (HK2) and the mTOR-STAT3 pathway in bladder cancer." (PMID 31416244, 2019). "In bladder carcinoma, lncRNA UCA1 is overexpressed and promotes glycolysis by upregulating hexokinase 2 (HK2), which promotes aerobic glycolysis and acts as the key indicator of the Warburg effect." (PMID 30134946, 2018). "In human bladder cancer cells, the expression of a long non-coding RNA UCA1 promoted glycolysis via a 0.5-fold increase in hexokinase 2 expression." (PMID 26887408, 2016). "Thus, overexpression of genes related to glycolytic processes, such as GLUT1, GLUT3, HK2, LDHA, and PKM, is common in bladder cancer tissues and cells." (PMID 37258572, 2023). "Furthermore, we used cryptotanshinone to inhibit the phosphorylation of Tyr 705 STAT3 in bladder cancer cells with knocking down or overexpressing GSDMB, resulting in constant protein and mRNA levels of HK2." (PMID 34326684, 2021). "Moreover, Western blot analysis showed that Vitamin K2 stepwise elevated the expression of some glycolytic proteins or enzymes, such as GLUT-1, Hexokinase II (HK2), PFKFB2, LDHA and PDHK1, in bladder cancer T24 and EJ cells." (PMID 32382009, 2020). "In bladder cancer, UCA1 could promote glycolysis by up-regulating hexokinase 2 through both activation of STAT3 and repression of miR-143." (PMID 30918102, 2019). "As indicated by recent studies, UCA1 activates mTOR by upregulating HK2 and increases glycolysis through both the activation of STAT3 and the repression of miR-143, thereby revealing a novel glucose metabolism regulatory pathway, UCA1-mTOR-STAT3/miR-143/HK2, in bladder cancer cells." (PMID 30134946, 2018). "In addition, miR-1 plays a tumor suppressive role via downregulating UCA1 in bladder cancer and UCA1 participates in cancer cell glucose metabolism through the cascade of mTOR-STAT3/miR143-hexokinase 2 (HK2), indicating a positive interaction between UCA1 and miRNAs in cancer cells." (PMID 25760077, 2015). "Here we identify a noncanonical, nuclear role of hexokinase 2 (HK2) that couples systemic hyperglycemia to MYC-driven glycolysis and stemness in bladder cancer." (PMID 41951587, 2026).
osteosarcoma (32 papers, 2015 to 2025). A usually aggressive malignant bone-forming mesenchymal neoplasm, predominantly affecting adolescents and young adults. "A number of 131 cases of sarcoma was analyzed and we found that HK2 and Glut1 high expression associated with poor prognosis in osteosarcoma patients, p = 0.023 and p = 0.013, respectively." (PMID 32831652, 2020). "Nevertheless, there is still a deficiency in the HK2 regulation system in osteosarcoma." (PMID 39661501, 2024). "As indicated by a previous study, TUG1 is associated with HK2-mediated glycolysis in osteosarcoma." (PMID 32331347, 2020). "TUG1 has also been associated with the HK2-mediating glycolysis regulating the viability ability of osteosarcoma cells, although the exact mechanism is unknown." (PMID 31850189, 2019). "Compared with that in adjacent tissues, HK2 protein and mRNA expression was significantly higher in osteosarcoma tissue, which was confirmed by immunohistochemical staining." (PMID 39661501, 2024). "Mechanistically, USP22 regulates HK2 by deubiquitination and stabilising the expression of β‐catenin, thereby controlling glycolysis in osteosarcoma cells." (PMID 39661501, 2024). "Mechanistically, USP22 regulates HK2 by deubiquitinating and stabilising β‐catenin expression, thereby promoting glycolysis in osteosarcoma cells." (PMID 39661501, 2024). "Knocking down HK2 reduces aerobic glycolysis, increases apoptosis, indicated that HK2 regulates the glycolytic pathway to promote osteosarcoma growth." (PMID 38586328, 2024). "In contrast, USP22 overexpression significantly increased the protein levels of HK2 and β‐catenin and promoted the proliferation and glycolytic rate of osteosarcoma cells." (PMID 39661501, 2024). "Previous studies indicate that HK2 is a classic downstream gene of β‐catenin in several tumours, including osteosarcoma." (PMID 39661501, 2024). "HK2 is a classic downstream gene of β‐catenin, regulating tumour glucose metabolism; however, its role in osteosarcoma is unclear." (PMID 39661501, 2024). "Overall, these results indicate that USP22 regulates HK2‐mediated glycolysis in osteosarcoma cells via β‐catenin." (PMID 39661501, 2024). "qRT‐PCR and western blot analysis showed that USP22 and HK2 were highly expressed in osteosarcoma tissues and were positively correlated." (PMID 39661501, 2024). "In the present study, USP22 knockdown markedly reduced the protein levels of HK2 and β‐catenin and strongly suppressed the proliferation and glycolytic rate of osteosarcoma cells." (PMID 39661501, 2024). "Further, to know the mechanism behind the HK2 reduction, we evaluated the PI3K-AKT levels because previously it was reported that PI3K-AKT induces glycolytic phenotype via HK2 in pediatric osteosarcomas." (PMID 35216429, 2022). "Song et al23 reported that lncRNA PVT1 is also involved in glucose metabolism and proliferation of osteosarcoma cells through the miR‐497/HK2 pathway." (PMID 32960485, 2021). "Glucose uptake, lactate production and the expression of HK2 are all increased in osteosarcoma cells with an overexpression of PVT1 and decreased by PVT1 knockdown." (PMID 33652661, 2021). "The overexpression of PVT1 enhances glucose metabolism via modulation of the miR-497/HK2 axis in osteosarcoma." (PMID 32331347, 2020). "PVT1 over expression increased glucose uptake, lactate production, and the expression of HK2 in osteosarcoma cells." (PMID 30083911, 2019). "Given that USP22 is positively associated with HK2, we speculate that USP22 modulates glycolysis in osteosarcoma cells by regulating the expression of HK2." (PMID 39661501, 2024). "In addition to promoting angiogenesis in ECs, PFKFB3 and HK2 are also crucially involved in the progression of osteosarcoma by regulating aerobic glycolysis." (PMID 39252946, 2024). "To confirm our hypothesis, we examined HK2 protein and mRNA expression in osteosarcoma cells following USP22 knockdown and overexpression." (PMID 39661501, 2024).